OCLN (occludin)
Diseases named in the same sentence as OCLN in open-access papers (continued):
Sharing a sentence is not in itself a finding about the gene and the disease.
infection (continued). "In addition, a significant cooperative relationship was observed for CLDN-3 and occludin (OCLN) gene expression levels between E. faecium supplementation and NE infection." (PMID 31311959, 2019). "With further in vivo and in vitro verification in response to infection, we demonstrated that meningitic E. coli-induced PDGF-BB negatively regulated the expression of TJ proteins including ZO-1, Occludin, and Claudin-5, enlarging endothelial permeability and causing BBB disruption." (PMID 31092253, 2019). "The transcript downregulation corresponded to a loss of tight junction complexes, as immunostaining revealed that occludin, claudin-5, and ZO-1 proteins were noticeably discontinuous or absent from cell-cell junctions following infection." (PMID 29104935, 2017). "Because Copenhageni-infection did not disturb occludin and claudin (tight junction markers), the VE-cadherin/catenin-complex at the adherens junction is likely to be the main target of pathogenic Leptospira species in endothelial cells." (PMID 28750011, 2017). "Although various signaling cascades that were involved in the inflammatory responses undergo changes in the expression patterns after LPS infection, the relationship among MKP-1, p38 and occludin displayed distinct interaction each other in the spatio-temporal manner." (PMID 27783995, 2016). "In addition, infectious titers in the culture supernatants at 72 h post-infection exhibited little decrease in SR-KO cells, in contrast to the much greater decreases in CD81, CLDN1 or OCLN KO Huh7 cells." (PMID 27152966, 2016). "The results of western blot analysis indicated that the protein expression levels of ZO‐1 and Occludin were significantly decreased in infected organoids compared to the control organoids without infection." (PMID 25214524, 2014). "To determine if the timing of action of HCV cell entry factors was influenced by HepG2 cell polarity, we used this synchronized cell infection assay to study the kinetics of entry factor usage in nonpolarized 786-O cells expressing the OCLN EC2-F5 mutant." (PMID 23555257, 2013). "Lentiviral expression of an shRNA targeting OCLN in HepG2+miR-122+CD81 cells efficiently silenced expression of endogenous OCLN and impaired infection with both HCVpp and HCVcc bearing the glycoproteins from the H77 genotype 1a and HC-J6 2a isolates, respectively." (PMID 23555257, 2013). "We confirmed that the EC2-F5 antibody inhibition was dose dependent and HCV specific, as the maximal amount of FLAG antibody tested did not impair VSVGpp infection of OCLN EC2-F5 cells or HCVpp infection of 786-O cells expressing wild type OCLN." (PMID 23555257, 2013). "Knocking-down OCLN in virus-prone T cell line inhibited HCV infection, while de novo infection downregulated OCLN and CD81, and upregulated CD5 without modifying SR-B1 expression." (PMID 23626783, 2013). "The inhibitors of COX1 and COX2 did not affect upregulation of claudin-4 and occludin after infection with RSV in Western blotting." (PMID 24058438, 2013). "HCV mainly targets hepatocytes and its infection is mediated by several entry cofactors located on the cell surface, including the tetraspanin CD81, the scavenger receptor class B member I (SR-BI), Claudin 1 (CLDN1), and Occludin (OCLN)." (PMID 23202463, 2012). "Indeed, fluorescence microscopy revealed alternated occludin distribution in Caco-2 monolayers upon infection with C. jejuni wt bacteria, but not with the isogenic ΔhtrA mutant." (PMID 38334616, 2024). "Additionally, PAstV–4 infection triggered the activation of the extracellular regulated protein kinases/ myosin light-chain kinase (ERK/MLCK) pathway, followed by the down-regulation of tight–junction proteins (occludin and ZO–1) as well as MUC–2 expression." (PMID 38891045, 2024).
infection (continued). "Meanwhile, dietary EOA treatment also upregulated CLDN-1, OCLN, ZO-1, MUC2 and FABP2 mRNA levels at the middle infection phase, as well as linearly reduced the gene expression level of TLR4, NF-κB and IL-1β at the early infection stage in infected broiler chickens." (PMID 37391807, 2023). "Moreover, junction molecules, namely, claudin-5, occludin, ZO-1, and VE-cadherin, which are essential proteins for maintaining the permeability of the BBB, were dramatically decreased in response to CV-A10 infection." (PMID 37577373, 2023). "Furthermore, the expression of other tight junction protein, such as CLDN2 and OCLN genes, were also significantly altered by the infection in conventional chickens compared to non-infected ones." (PMID 37680750, 2023). "Nevertheless, a detachment of cell-cell contacts at the TJs domain was observed after infection with HlyA-secreting E. coli, whereas in HDM controls or in uninfected control Caco-2 cells a sharp TJ meshwork pattern with a proper colocalization of occludin with ZO-1 was visible." (PMID 34437391, 2021). "VA1 infection had no impact on occludin relocalization even at an MOI of 10, nor did it impact TER." (PMID 33673521, 2021). "More specifically, as an immunomodulatory nutrient, glutamine regulate tight junction proteins (occludin, claudin-1, and zona occludens-1), controls chain reactions of cytokines such as TNF-α and IL-17A, and increases local secretory IgA (sIgA) production for preventing infection." (PMID 33143293, 2020). "While the EspF–SNX9 interaction is important for barrier disruption in SKCO-15 and Caco-2, it does not play a role in T84 cells, as infection with the EspF-D3 mutant failed to protect against a loss of TER and the redistribution of occludin in polarized T84 cells." (PMID 31947656, 2020). "Finally, to assess the involvement of 5-HT2AR in HCV cell entry in vivo, we evaluated the ability of ezetimibe to inhibit infection of a genotype 2a (JC-1) in immune-competent humanized transgenic mice of chronic HCV infection harboring both human CD81 and OCLN genes (C/OTg)." (PMID 29542010, 2019). "It was also found that an infection with EPEC reduced significantly the TJ proteins (occludin (phosphorylated form), ZO-1 and claudin-1), which is supported by other findings reporting a rapid and progressive dephosphorylation of occludin following EPEC infection." (PMID 28208612, 2017). "However, the four peptides did not interact with HCV receptors (SRB1, claundin-1, CD81 and occludin), consistent with the lack of antiviral activity of these four peptides when incubated with the cells before infection." (PMID 28638089, 2017). "However, occludin expression was not significantly different between saline and eptifibatide treated, EcoHIV-infected mice, one month post-infection." (PMID 26986758, 2016). "As in 293T cells, 786-O cells expressing OCLN proteins were not permissive to HCVpp infection." (PMID 26561856, 2015). "Similarly, infection of porcine intestinal epithelial cells (IPEC-J2) with porcine epidemic diarrhea virus (PEDV) and transmissible gastroenteritis virus (TGEV) altered expression of ZO-1 and occludin, 1 h post infection, which correlated with increased permeability across the epithelial cell layer." (PMID 35328419, 2022). "Compared to the control STEC monolayers, the continuous tight junction structures of ZO-1 and occludin in HPS4-YC-infected cells were destroyed and could hardly constitute cell–cell junctions, which indicate that the integrity of the TJ ZO-1 and occludin were disrupted after HPS4-YC infection." (PMID 34674760, 2021). "Moreover, infection did not appear to induce the cleavage of occludin." (PMID 33935732, 2021). "Treatment with dynasore did not prevent the endocytosis of occludin or the decrease in TER caused by EPEC at 1–2 h post-infection (–15.0 ± 3.0% vs. –14.0 ± 2.0%; –36.0 ± 5.0% vs. –30.0 ± 2.0%, with and without dynasore at 1 and 2 h post-infection, respectively)." (PMID 31947656, 2020).
infection (continued). "In addition, such differences were not influenced by cell polarity and were also observed with HCVpp, as pseudoparticles bearing the glycoproteins from a subset of these isolates exhibited similar OCLN usage and antibody blocking patterns when tested in nonpolarized 786-O cell infections." (PMID 23555257, 2013). "Epithelial transcription of tight junction proteins ZO-1 and occludin, and permeability to FITC-dextran were also not affected by infection." (PMID 40586572, 2025). "The relative mRNA expressions of jejunal tight junction proteins were not significantly affected by the interaction of the diet × infection and main effects of diets, except for the main effects of infection on JAM-2 and a tendency (P < 0.10) for occludin." (PMID 41130050, 2025). "To further rule out that the expression of tight junction proteins is not altered in response to infection, we conducted qPCR to assess the expression of the tight junction proteins ZO-1 (TJP1) and occludin (OCLN)." (PMID 38756230, 2024). "We did not observe a noticeable difference in OCLN and ZO1 in mRNA abundance during the peak infection." (PMID 39759108, 2024). "Confirming the functional role of OCLN in HCV entry, previous mechanistic monoclonal antibodies targeting ECL2 of OCLN were efficient in the prevention of infection both in cell culture and human liver chimeric mice without detectable side effects." (PMID 32012812, 2020). "The infection with EcoHIV did not alter the MFI values for claudin-5 and occludin; however, ZO-1 levels were diminished as compared to mock infection." (PMID 28008980, 2016). "The upregulation of claudin-4, occludin and PKR after infection with RSV was not affected by any dose of salubrinal." (PMID 24058438, 2013). "While the EC2-F2 and EC2-F3 OCLN mutants functioned well for all viruses except SA13 5a HCVcc, only HK 6a HCVpp infection of EC2-F3 expressing cells was inhibited, although not significantly, by FLAG antibody." (PMID 23555257, 2013). "Furthermore, OCLN and JAM1 were significantly downregulated upon indirect infection with wild-type C. albicans but not the Cacfl11Δ mutant." (PMID 41590450, 2026). "Upon infection, ICP0-expressing cells were detected at 3 h postinfection (hpi) under short-term (1 day) differentiation conditions, while only single apical cells with no continuous ZO-1 or occludin stainings were infected after 8 days of differentiation." (PMID 37289055, 2023). "Although it is not clear why SARS-CoV-2 infection down-regulates both the production and stability of the OCLN protein, both phenomena appear to be dependent on SARS-CoV-2 infection and replication since infection with UV-inactivated SARS-CoV-2 does not affect either OCLN distribution or expression." (PMID 37068248, 2023). "This differential effect of HCV infection on the expression of CD81, OCLN and CD5, but not SR-B1 gene, provided supporting evidence that the respective proteins might be engaged in the infection process induced by HCV in T cells." (PMID 23626783, 2013). "Furthermore, we observed that FLAG antibody induced an even greater degree of internalization of the OCLN EC2-F3 mutant (‘EC2-F3’), even though the antibody did not impair HCVpp infection of cells expressing this mutant." (PMID 23555257, 2013). "After infection with E. coli K99, the expression of P. pentosaceus SNF15, Claudin-1, MUC2, and ZO-1 in oral administration increased significantly compared with the CN group (p < 0.05), and the expression level of occludin did not change significantly (p > 0.05)." (PMID 40151573, 2025). "The infection time of SS2 was based on the results in preliminary experiments, the protein levels of ZO-1 and occludin in STEC infected with SS2 for 4, 8 and 12 h were not reduced, while SS2 infection could affect the distribution of TJ (these data have not been published)." (PMID 32106883, 2020).
tumor (127 papers, 2006 to 2026). "Our data demonstrate significant levels of occludin expression in many different tumor entities and identify loss of occludin expression as a potentially useful prognostic marker in several tumor entities." (PMID 40173205, 2025). "In this study, OCLN expression was found to be significantly negatively correlated with PDCD1 and CTLA4 expression, which implicated the role of OCLN in regulating tumor immunology in KIRC." (PMID 37809090, 2023). "In one particular study, Gremlin and α-SMA expressing CAFs in colorectal cancers were observed near the tumor invasive front where tumor cells showed nuclear accumulation of β-catenin and the loss of the tight junction protein occludin." (PMID 32486027, 2020). "Loss of E-cadherin is considered as an important hallmark of EMT and downregulation of occludin has been shown to be closely linked with the metastasis of tumor cells and has been found to be associated with EMT progression." (PMID 30004418, 2018). "Loss of the TJ proteins occludin and claudins enhances tumor progression via cell migration and invasion." (PMID 27036040, 2016). "The expression and dysfunction of occludin proteins is associated with the development and metastasis of tumor." (PMID 24992189, 2014). "In the digestive tract, a reduction in or abnormal distribution of occludin is associated with the progression of tumor." (PMID 24066055, 2013). "It has been reported that loss of certain tight junctional molecules, such as ZO-1, ZO-2, and occludin are frequently seen in clinical tumours and the loss of these TJ molecules is associated with the aggressiveness of tumours." (PMID 16430777, 2006). "The down-regulation of tight junction proteins claudin-1, occludin, and ZO-1 may be associated with tumor proliferation, invasion, and metastasis." (PMID 39465423, 2024). "The loss of occludin enhances tumor progression via cell migration and invasion." (PMID 28071680, 2017). "It has been observed that tumor tissues have truncated or variant signals of occludin." (PMID 27547510, 2016). "In fact, accumulating evidence has already indicated that the cleavage of tight and adhesion junction proteins, such as Occludin and E-cadherin, in tumor cells supports cancer cell migration, invasion, and metastasis." (PMID 40034591, 2025). "In terms of specific communication signals, tumor-associated ductal cells increase the output of signals such as ALCAM and OCLN and the input of signals such as CD96 and CD6." (PMID 40688078, 2025). "At least an occasional weak occludin positivity was detected in 134 of 148 (90.5%) tumor types and tumor subtypes and 108 (72.9%) entities included at least one case with strong occludin positivity." (PMID 40173205, 2025). "Downregulation of adherens junction and tight junction proteins such as claudin, occludin, and E-cadherin disrupts cell adhesion and promotes the migration of tumor cells, thereby playing a key role in tumor metastasis." (PMID 40002176, 2025). "The data from our successful analysis of 14,017 tumors from 148 different tumor categories provide a comprehensive overview of occludin expression in cancer." (PMID 40173205, 2025). "The neovascularization of brain metastases is regulated by tumor‐derived factors, which downregulate the expression of tight junction proteins, such as ZO‐1 and Occludin, in endothelial cells, leading to increased BBB permeability." (PMID 41245887, 2025). "Our data demonstrate significant levels of occludin expression in many different tumor entities and identify reduced occludin expression as a potentially useful prognostic feature in several tumor entities." (PMID 40173205, 2025). "Mechanistically, E-cadherin restoration suppresses metastatic dissemination through transcriptional repression of N-cadherin via ZEB1/2-mediated pathways, while ZO-1 and occludin reinforce intercellular tight junctions to impede tumor cell intravasation." (PMID 40136409, 2025).
tumor (continued). "Preclinical findings showed that EIN significantly reduced tumor volume (P < 0.05) and preserved the integrity of the intestinal mucosal barrier, evidenced by higher ZO-1 and Occludin expression (P < 0.05)." (PMID 41387645, 2025). "Glabridin inhibits EMT by upregulating epithelial markers (E-cadherin, occludin) and downregulating mesenchymal markers (vimentin, Zeb1), effectively reducing tumor metastasis." (PMID 39723390, 2024). "As some members of the zonula occludens proteins are thought to enable intrahepatic extravasation of circulating tumor cells, we analyzed the expression of the genes Claudin-2 and -5 as well as Occludin and ZO-1 in liver tissues in this mouse model." (PMID 38919609, 2024). "In the TCGA-KIRC clinical cohort, the expression level of OCLN was negatively related to tumor grade, clinical stage, T stage and M stage." (PMID 37809090, 2023). "Several studies have reported that loss of bTJ proteins, including claudins (CLDNs) and occludin (OCLN), enhances tumor progression." (PMID 36961882, 2023). "The tumor growth-promoting and metastatic effects of OCLN have also been demonstrated in prostate cancer, and the presence of lymphatic dissemination is also observed in the metastatic process." (PMID 37809090, 2023). "The expression of OCLN was significantly related to tumor grade, clinical stage, T stage, and M stage in KIRC patients." (PMID 37809090, 2023). "Four weeks after intracranial injection of U87MG cells to establish a 1 mm3 tumor volume, degradation of tight junctions was confirmed through assessment of occludin as a tight junction marker." (PMID 37723574, 2023). "The protein expression of OCLN was decreased in KIRC tissue samples, and the immunohistochemistry staining further verified that the expression of OCLN was lower in tumor tissues." (PMID 37809090, 2023). "Occludin integrates such diverse processes as gene transcription, tumor suppression, and cell proliferation to modulate the intestinal mucosal structure and function." (PMID 36846248, 2023). "Consistent with the results obtained from the TCGA, IHC analysis showed higher OCLN expression in BLCA tumours than in adjacent tissues, and OCLN expression was higher in patients with advanced tumours than in non‐advanced patients." (PMID 35224833, 2022). "In pathological samples and mouse xenograft models, OCLN was positively correlated with tumour angiogenesis." (PMID 35224833, 2022). "Consistent with the changes in serum CCL2 and CCL5 in tumor-bearing mice, there were corresponding changes in ZO-1, Occludin and phosphorylated p38 protein levels in these premetastatic mouse lungs." (PMID 36438499, 2022). "TUNEL assay was used to observe the apoptosis of tumor tissues, and immunohistochemistry was used to observe the expression of Ki-67 and occludin." (PMID 35873550, 2022). "Previous studies have also found that ZC3H13 inhibits the Ras-ERK signaling pathway, reduces the expression of Snail, Cyclin D1, and Cyclin E1, and upregulates the expression of occludin and Zo-1, thereby inhibiting tumor progression." (PMID 38024481, 2022). "Taken together, these results indicated that OCLN controls tumour angiogenesis by regulating p‐STAT3 levels in BLCA cells through effects on IL8 expression." (PMID 35224833, 2022). "Downregulation of OCLN inhibits tumour angiogenesis in BLCA cells and murine xenografts, whereas OCLN overexpression exerts the opposite effect." (PMID 35224833, 2022). "Because tumour development is based on tumour angiogenesis, which provides essential nutrients for tumour growth, we knocked down and overexpressed OCLN to detect the function of OCLN." (PMID 35224833, 2022). "Tumor-bearing mice had lower expression of tight junction proteins Claudin-1 (Cldn1) and Occludin (Ocln) in the colon, while Resected mice only had lower expression of Ocln (but tended to have lower Cldn1) relative to Control mice." (PMID 35248004, 2022).